LAPTM4B (lysosomal protein transmembrane 4 beta)
Diseases named in the same sentence as LAPTM4B in open-access papers (continued):
Sharing a sentence is not in itself a finding about the gene and the disease.
tumor (continued). "Further examination of the tumor samples by western blotting revealed decreased LAPTM4B levels in mice tumor samples treated with “copanlisib” or “combination”." (PMID 41362742, 2026). "To investigate the clinical association of LAPTM4B and ATP1A1 with acquired EGFR-TKI resistance, we further analyzed paired tumor biopsies from six patients with EGFR-mutant NSCLC collected before treatment and after acquisition of EGFR-TKI resistance." (PMID 41362742, 2026). "LAPTM4B+ stem‐like cells are closely linked to CRC progression, contributing to tumor stratification through their interplay with LGR5+ stem‐like cells." (PMID 40661135, 2025). "Bulk RNA‐seq analysis of the FAHNU‐BULK cohort (n = 148) revealed significantly elevated LAPTM4B expression in tumor tissues compared to adjacent normal tissues (p < 0.0001)." (PMID 40661135, 2025). "We found that LAPTM4B expression was positively related to immune regulatory genes in majority tumor types, especially in PRAD, UVM, THYM, LIHC, BLCA, and OV." (PMID 40092987, 2025). "This study identified the existence of a novel population of LAPTM4B+ tumor stem‐like cells in addition to the classical LGR5+ tumor stem‐like cells in colorectal cancer (CRC)." (PMID 40661135, 2025). "To assess the potential correlation between elevated LAPTM4B expression and the drug response of tumor cells, we conducted Spearman correlation coefficient analysis using data from the GDSC dataset." (PMID 40092987, 2025). "Across multiple CRC cohorts, LAPTM4B expression was positively correlated with tumor proliferation and stemness." (PMID 40661135, 2025). "To evaluate the association of LAPTM4B expression with TME in Ph+ B-ALL, we conducted an ESTIMATE analysis to calculate the stromal score, immune score, ESTIMATE score, and tumor purity within Ph+ B-ALL." (PMID 40092987, 2025). "Sparse LAPTM4B+ populations were also present in healthy intestinal tissues, and transcriptional similarities between rare Tuft cells and tumor stem‐like subsets were identified." (PMID 40661135, 2025). "In contrast, tumor cells depleted for LAPTM4B were protected against anthracycline- or paclitaxel-induced Poly (ADP-ribose) polymerase (PARP) cleavage." (PMID 40231269, 2025). "Both tumor stem‐like cell populations were predominantly localized to tumor tissues, and only sparse LAPTM4B+ cells were detectable in normal intestinal tissues." (PMID 40661135, 2025). "PCR assays were performed on 92 paired samples of HCC tumor and adjacent normal tissues from The Affiliated Hospital of Qingdao University for validation; thus, LAPTM4B expression significantly increased in HCC tissues (P < 0.001)." (PMID 38388484, 2024). "To evaluate the level of ferroptosis, we measured the amounts of MDA, our data indicated that patients’ tumor samples with low expression of either LAPTM4B or SLC7A11 had higher MDA levels." (PMID 38902268, 2024). "Various cellular assays and animal experiments strengthen the notion that LAPTM4B protects tumor cell growth from erastin-induced ferroptosis both in vitro and in vivo." (PMID 38902268, 2024). "Our results showed that LAPTM4B counteracts erastin-induced ferroptosis in vitro and tumor growth in vivo." (PMID 38902268, 2024). "The animal experiments further support this notion, as combined treatment of ferroptosis inducers with LAPTM4B depletion resulted in a significant reduction of tumor growth with negligible side effects." (PMID 38902268, 2024). "Through a series of cell-based assays and animal experiments, we demonstrate that LAPTM4B protects tumor cells from erastin-induced ferroptosis both in vitro and in vivo." (PMID 38902268, 2024). "LAPTM4B is crucial for regulating tumor suppression, tumor cell proliferation, invasion, metastasis, apoptosis resistance, autophagy initiation, and drug resistance." (PMID 38388484, 2024). "Further examination of the tumor samples by immunohistochemistry revealed increased SLC7A11 staining in LAPTM4B-positive tumor samples." (PMID 38902268, 2024).
tumor (continued). "LAPTM4B affected PD-L1 receptor expression in tumor microenvironment and enhanced tumor suppression induced by PD-L1 monoclonal antibodies in HCC patients." (PMID 38388484, 2024). "Collectively, these observations established that LAPTM4B depletion enhances the anti-tumor growth effect of erastin in vivo." (PMID 38902268, 2024). "We acquired diverse tumor data from TCGA and identified LAPTM4B up-regulation in 12 of 33 tumor types, including Liver Hepatocellular Carcinoma (LIHC) (p < 0.0001)." (PMID 38388484, 2024). "For example, the lysosomal-associated protein transmembrane 4 beta (LAPTM4B) gene has been found to be upregulated in HCC tissues, and its expression is associated with poor prognosis and increased tumor aggressiveness." (PMID 38114725, 2023). "The immune differences between the two groups were compared, correlation between LAPTM4B and immune cells was also compared, and the activity differences in ccRCC tumor cells were compared using a single-cell study." (PMID 36937841, 2023). "Analyzing data from the Gene Expression Omnibus (GEO) database revealed that LAPTM4B was upregulated in OS tumor tissues compared with normal control tissues (GSE99671, GSE126209)." (PMID 37147294, 2023). "According to a previous research, LAPTM4B promotes tumor growth and autophagy in HCC cells by activating ATG3 transcription." (PMID 38114725, 2023). "Overexpression of ATAD2 and PVT1 in 8q24.13, RAD54B, LAPTM4B, and RRS1 in 8q21.13 were reported to be associated with tumor proliferation and progression of HCC." (PMID 36010950, 2022). "In the same line, the oncogene LAPTM4B (Lysosomal Protein Transmembrane 4 Beta) plays several roles in carcinogenesis, such as promoting tumor growth and metastasis, inhibiting apoptosis, initiating autophagy and driving multidrug resistance mechanisms." (PMID 33854980, 2021). "Subsequently, tumor tissue samples were classified into two groups, LAPTM4B high‐expression and low‐expression groups, according to the staining intensity of LAPTM4B." (PMID 32558212, 2020). "We further explored the potential effects of LAPTM4B on tumor growth and metastasis using in vivo animal model." (PMID 32558212, 2020). "Then we detected the expression levels of LAPTM4B in tumor tissues from mice, and western blot assays showed that the expression of LAPTM4B in knockdown groups was obviously reduced compared with the control." (PMID 32558212, 2020). "The aim of this study was to evaluate LAPTM4B-35 protein as a new prognostic marker for HNSCC in primary tumours and lymph node metastases and correlate results with clinical data." (PMID 31827181, 2019). "This study is the first to investigate the HNSCC expression of LAPTM4B-35 in primary tumours and metastasis on the protein level." (PMID 31827181, 2019). "This study provides preliminary evidence directing towards the utilization of co-expressional profiles of HIF-1α, MDR1 and LAPTM4B as potential candidate for serum based biomarkers for tumor progression however warranting further clinical surveillance." (PMID 30746305, 2019). "In the patient group with low primary tumour LAPTM4B-35 expression, 28 (38.8%) had low expression in the lymph node metastasis and 7 (9.7%) patients showed a high expression profile." (PMID 31827181, 2019). "In 19.4% of cases, high LAPTM4B-35 expression was observed in both the primary tumour and corresponding lymph node metastases." (PMID 31827181, 2019). "Hazard ratios in relation to LAPTM4B-35 expression, tumour localization, HPV infection, sex, age and classification (T and N) were calculated." (PMID 31827181, 2019). "Increased expression of HIF-1α, MDR1 and LAPTM4B was observed with higher tumor stage and distant metastasis (p < 0.05)." (PMID 30746305, 2019). "The elevated expression of HIF-1α, MDR1 and LAPTM4B was found to be correlated with advanced tumor stage and metastasis (p < 0.05)." (PMID 30746305, 2019).
tumor (continued). "Further functional assay indicated LAPTM4B plays an important role in tumor proliferation and metastasis in LAC." (PMID 30940109, 2019). "LAPTM4B has been shown to boost tumour growth and cell proliferation by activating related signalling pathways in various kinds of tumours." (PMID 29337428, 2018). "Our results suggested that Huh7 cells with AP4 knockdown significantly suppressed tumour growth, but the effect was partially reversed by overexpression of LAPTM4B (Fig. 4D1,D2,E)." (PMID 29337428, 2018). "A number of studies have shown that the proliferation of cells overexpressing LAPTM4B is closely correlated with tumor progression and metastasis." (PMID 28476037, 2017). "What's more, our data indicated that the increased LAPTM4B-35 protein level correlated with tumor recurrence (p = 0.031)." (PMID 27486880, 2016). "The in vivo bioimaging study also manifests that after 1 h post intravenous injection of DBT-2EEGIHGHHIISVG, the probe has the capacity in selective visualization of LAPTM4B protein-expressed tumour tissues in live mice." (PMID 26984064, 2016). "Conversely, knockdown of endogenous LAPTM4B-35 expression with RNAi reverses all of these malignant cellular and molecular phenotypes in vitro, and inhibits tumor growth and metastasis of human HCC xenograft in nude mice." (PMID 27542271, 2016). "Overexpression of LAPTM4B-35 upregulates expression of a number of oncogenes, and downregulates expression of some tumor suppressing genes." (PMID 27542271, 2016). "On histological sections, xenograft tumours expressing miR-188-5p showed decreased staining for LAPTM4B-35." (PMID 25714029, 2015). "To assess the role of LAPTM4B on tumour metastasis in vivo, we measured metastases exclusively in the cervical lymph nodes." (PMID 25714029, 2015). "Up-expression of LAPTM4B inhibits lysosome-mediated death pathways, promotes autophagy and leads to stress tolerance, thereby enhancing tumor cell growth, survival and resistance to apoptosis." (PMID 25932367, 2015). "Our data further demonstrated that the tumour-suppressive miR-188-5p targets LAPTM4B and that silencing of LAPTM4B significantly inhibits the proliferation, migration and invasion of PC-3 and LNCaP cells." (PMID 25714029, 2015). "Consistent with this in vitro data, restoration of LAPTM4B significantly reversed the suppression of tumour growth and metastasis induced by miR-188-5p." (PMID 25714029, 2015). "Accordingly, the effect of LAPTM4B-35 on the invasiveness of tumor cells was studied using the transwell assay." (PMID 25849595, 2015). "LAPTM4B-35 promotes tumor growth and tolerance to metabolic and genetic stress through the induction of autophagy." (PMID 25849595, 2015). "In order to assess the role of miR-188-5p on tumour growth in vivo, we examined miR-188-5p-mediated tumorigenesis in a murine xenograft model using control, miR-188-5p+LAPTM4B PC-3 and LNCaP cells, and PC-3 and LNCaP cells expressing miR-188-5p." (PMID 25714029, 2015). "In our present study, we found that LAPTM4B-35 positive expression generally correlated with worse prognosis in GC patients stratified by tumor stage or lymphovascular invasion." (PMID 25849595, 2015). "This association of genotype with clinicopathologic findings and prognosis is consistent with the putative role LAPTM4B plays in carcinogenesis and tumor progression." (PMID 22509374, 2012). "Importantly, in a mouse xenograft model, the combination of gefitinib and a LAPTM4B suppressor significantly reduced tumor growth with minimal toxicity." (PMID 41362742, 2026). "Interestingly, the expression of LAPTM4B positively correlated with the ATP1A1 levels in these tumor samples from nude mice." (PMID 41362742, 2026). "In general, these results suggested that LAPTM4B might regulate immune cell infiltration and immune-related genes functions in most tumor types." (PMID 40092987, 2025).
tumor (continued). "To investigate whether LAPTM4B expression levels are associated with TMB, MSI, and tumor purity, we conducted analyses using Spearman correlation analysis." (PMID 40092987, 2025). "Meanwhile, LAPTM4B knockdown inhibited tumor cell migration and invasion, possibly by downregulation of related proteins such as matrix metalloprotein 2 (MMP-2), matrix metalloprotein 9 (MMP-9), cell cycle-dependent protein kinase 12 (CDK12) and Hypoxia-inducible factor 1-alpha (HIF-1α)." (PMID 40231269, 2025). "mIHC was performed to simultaneously assess LGR5 and LAPTM4B expression in 71 CRC tumor samples." (PMID 40661135, 2025). "LAPTM4B also regulates various cell signaling pathways, interacts with autophagy-related proteins and ceramides, and regulates the autophagy process and the release of exosomes, which in turn affect the survival and drug resistance of tumor cells." (PMID 40231269, 2025). "Besides, we found that increased LAPTM4B expression led resistance to a broad spectrum of therapeutic agents in tumor cells." (PMID 40092987, 2025). "The probe DBT-2EEGIHGHHIISVG enables the targeted visualization of LAPTM4B in human HCC cells, and selective and high-contrast imaging of LAPTM4B protein-expressing tumor tissues in live mice, which has the potential to make LAPTM4B useful in the treatment of HCC." (PMID 40231269, 2025). "Moreover, immune infiltration scores of tumor-infiltrating lymphocytes (TILs) type in different LAPTM4B expression groups were also evaluated using ssGSEA." (PMID 40092987, 2025). "Tumor samples show elevated transcript expression of both LAPTM4B and SLC7A11." (PMID 38902268, 2024). "LAPTM4B protein expression was verified on samples in 42 patients from The Affiliated Hospital of Qingdao University by Western-blotting assay, and LAPTM4B expression was significantly elevated in tumor tissues." (PMID 38388484, 2024). "Tumors were removed and examined on day 28, revealing increased LAPTM4B-Lv tumor size." (PMID 38388484, 2024). "LAPTM4B overexpression increased tumor diameter and quantity." (PMID 38388484, 2024). "Additionally, we examined LAPTM4B levels in tumor and paired-normal tissue from seven patients, the results confirmed LAPTM4B is upregulated in OS tumor tissue." (PMID 37147294, 2023). "The LAPTM4B gene was overexpressed in tumor tissues of the luminal A, luminal B, and TNBC subtypes." (PMID 37176055, 2023). "Finally, the effects of LAPTM4B on the proliferation, apoptosis, and metastasis of tumor cells in ccRCC were verified using cell experiments." (PMID 36937841, 2023). "Finally, we verified the correlation between LAPTM4B expression and tumor cell proliferation and metastasis using cell-based experiments." (PMID 36937841, 2023). "In addition to its regulatory function in a variety of tumors, LAPTM4B also has several important physiological functions in non‐tumor cells." (PMID 32558212, 2020). "Moreover, there was a significant correlation between LAPTM4B and tumor size (P = 0.001) as well as between YKL-40 and TNM staging (P= 0.008) in the same group." (PMID 32102511, 2020). "In addition, LAPTM4B has been reported to promote proliferation and metastasis of tumor cells, resist apoptosis, initiate autophagy and assist drug resistance." (PMID 30940109, 2019). "HIF-1α and LAPTM4B expression was correlated with tumor stage (p < 0.05)." (PMID 30746305, 2019). "Taken together, these results suggested that PI3K/AKT and EMT pathways may mediate the pro-tumor effects of LAPTM4B in LAC cells." (PMID 30940109, 2019). "LAPTM4B-35 in the primary tumour was highly expressed in 47.2% of the patients (60/127)." (PMID 31827181, 2019). "Our results suggested that AP4 could increase HCC cell proliferation and tumour growth via LAPTM4B in vitro or in vivo." (PMID 29337428, 2018). "Moreover, there was a significantly positive correlation between LAPTM4B and VEGF expression levels and the probability of tumor-associated venous thrombus (P=0.012 and P<0.001, respectively)." (PMID 28476037, 2017).
tumor (continued). "What was more, LAPTM4B-35 played critical role in tumorigenesis and tumor metastasis." (PMID 27486880, 2016). "Furthermore, the in vivo bioimaging study using a tumour-bearing mouse model reveals that DBT-2EEGIHGHHIISVG can also serve as an FR/NIR fluorescence light-up probe to selectively visualize the LAPTM4B protein-expressed tumour." (PMID 26984064, 2016). "On a functional basis, LAPTM4B promotes autophagy, a cell survival mechanism mediated by lysosomes that renders tumor cells resistant to metabolic and genotoxic stress, which promotes a faster tumor growth rate." (PMID 25881887, 2015). "Moreover, knockdown of LAPTM4B mRNA using siRNA resulted in increased sensitivity of tumor cells to anthracyclines, an intercaling agent and a free radical inducer." (PMID 25881887, 2015). "Kaplan-Meier curves stratified by LAPTM4B-35 expression and tumor stage or lymphovascular invasion revealed that LAPTM4B-35 positive patients have significantly poorer OS compared with LAPTM4B-35 negative ones in TNM stages I-III or without lymphovascular invasion subgroup." (PMID 25849595, 2015). "The molecular mechanisms of LAPTM4B-35 in tumor progression properties are still unclear." (PMID 25849595, 2015). "In addition, our results indicate a significant association between the LAPTM4B polymorphism and cancer susceptibility in the subgroups stratified by control source, cancer type, tumor stage based on TNM, and tumor histopathologic differentiation." (PMID 24746178, 2014). "All of these results indicate that LAPTM4B may be an important biomarker for tumor initiation and development." (PMID 24746178, 2014). "The close relationship between LAPTM4B-35 overexpression and clinicopathological features predicted that LAPTM4B-35 might play an important role in carcinogenesis and tumor progression." (PMID 24651764, 2014). "Additionally, tumor samples from one patient (Patient #1) were also snap-frozen at the time of collection, allowing for immunoblot analysis, which independently suggested the upregulation of LAPTM4B following the development of EGFR-TKI resistance." (PMID 41362742, 2026). "The ability of LAPTM4B to modulate key signaling pathways, such as PI3K/AKT and EGFR, and affect autophagy and chemoresistance, and its ability to interact with autophagy-associated proteins and ceramides, further illustrates the complexity of the role of LAPTM4B in tumor cell survival." (PMID 40231269, 2025). "Thus, LAPTM4B-secreted CXCL8 drove MDSCs migration into tumor tissues." (PMID 38388484, 2024). "Therefore, LAPTM4B drove MDSCs migration toward tumor tissue primarily via CXCL8." (PMID 38388484, 2024). "In addition, IHC staining of transplanted tumor tissue sections revealed that both the inhibition of autophagy and suppression of proliferation caused by HDAC2 knockdown were reversed by ectopic expression of LAPTM4B." (PMID 39147759, 2024). "Moreover, the observed low expression of miR-137 in OS tumor samples, together with the functional assays in vitro and in vivo, indicate that this miRNA displays an instrumental regulatory role in migration and metastasis via controlling LAPTM4B expression." (PMID 37147294, 2023). "However, we found that the expression levels of LAPTM4B in tumor tissues was obviously correlated with tumor size and clinical stage, with the P‐values of 0.004* and 0.035*, respectively, suggesting a significant correlation between LAPTM4B expression and these clinical features." (PMID 32558212, 2020). "Moreover, we examined the relationship between c‐myc, AP4 and LAPTM4B and found a c‐myc‐AP4‐LAPTM4B‐positive feedback loop that may also be a pivotal factor in HCC tumour survival." (PMID 29337428, 2018). "Because AP4 was shown to positively regulate LAPTM4B expression, affecting transcription of LAPTM4B allele*2 to a greater extent, we speculated that AP4 may be a key regulator in the LAPTM4B transcription process, thereby affecting LAPTM4B function on tumours." (PMID 29337428, 2018).